MALAT1 (metastasis associated lung adenocarcinoma transcript 1)
Diseases named in the same sentence as MALAT1 in open-access papers (continued):
Sharing a sentence is not in itself a finding about the gene and the disease.
primary immunodeficiency (1 paper, 2022). "We further performed GO and KEGG enrichment analyses on the core lncRNAs and mRNAs and found that OIP-AS1 KEGG was mainly enriched in the IL-17 signaling pathway and MALAT1 in the primary immunodeficiency pathway." (PMID 36032150, 2022).
pulmonary edema (1 paper, 2021). Accumulation of fluid in the lung tissues causing disturbance of the gas exchange that may lead to respiratory failure. "DEX treatment alleviated severe pulmonary edema in ALI rats and overexpression of lncRNA MALAT1 enhanced the remission effect of DEX." (PMID 34516310, 2021).
rectal mucinous adenocarcinoma (1 paper, 2013). "Our Oncomine search confirmed MALAT-1 overexpression in various tumor entities, with the highest levels of MALAT-1 overexpression observed in rectal mucinous adenocarcinoma (6-fold overexpression compared with normal tissue)." (PMID 23717670, 2013).
rectum adenocarcinoma (1 paper, 2020). An adenocarcinoma arising from the rectum. "Similarly, MALAT1 was also higher in rectum adenocarcinoma (READ)." (PMID 33344634, 2020).
Respiratory distress (1 paper, 2022). Respiratory distress is objectively observable as the physical or emotional consequences from the experience of dyspnea. "The deficiency in Malat1 improved most of these latter readouts, in addition to enhance the coefficient of O2 extraction, indicating that the lack of Malat1 attenuated clinical signs of respiratory distress by improving gas exchange." (PMID 36105289, 2022).
respiratory system cancer (1 paper, 2016). "A significant relationship was observed between MALAT1 overexpression and poor OS in the studies for digestive system cancers (pooled HR = 1.77, 95 % CI 1.18–2.35), urinary system cancers (pooled HR = 2.95, 95 % CI 1.43–4.46), and respiratory system cancers (pooled HR = 1.72, 95 % CI 0.86–2.57)." (PMID 27777857, 2016).
rhabdomyosarcoma (1 paper, 2017). A rare aggressive malignant mesenchymal neoplasm arising from skeletal muscle. "A qRT-PCR analysis detected three lncRNAs—rhabdomyosarcoma 2-associated transcript (RMST), Tuna, and metastasis-associated lung adenocarcinoma transcription (MALAT1)—that were expressed in the 40NSCs and 37OCM groups." (PMID 28234910, 2017).
Right ventricular hypertrophy (1 paper, 2026). In this case the right ventricle is more muscular than normal, causing a characteristic boot-shaped (coeur-en-sabot) appearance as seen on anterior- posterior chest x-rays. "In vivo, adenoviral MALAT1 overexpression attenuated PH, right ventricular hypertrophy (RVH), vascular remodeling, and reduced ET-1 and VCAM1 expression in SS mice." (PMID 41597229, 2026).
schistosomiasis (1 paper, 2024). An infectious disease caused by parasitic trematodes of the genus Schistosoma that colonize human blood vessels and release eggs that can cause granulomatous reactions leading to acute (swimmer's itch or acute schistosomiasis syndrome) or chronic disease. "Gain- or loss-of-function experiments in vitro and in Malat1-KO mouse models in vivo revealed its suppressive effect on the progression of schistosomiasis HF through Malat1/miR-96/Smad7 axis." (PMID 39363237, 2024). "This study demonstrates that S. japonicum infection-induced downregulation of Malat1 expression contributes to schistosomiasis HF via the Malat1/miR-96/Smad7 axis." (PMID 39363237, 2024). "Elevated lncRNA Malat1 expression in infected HSCs reduces fibrosis via the Malat1/miR-96/Smad7 pathway, thus providing a novel therapeutic target for schistosomiasis HF." (PMID 39363237, 2024). "The Malat1-mediated suppression of schistosomiasis HF likely occurs through interaction with miRNA-96 located in the cytoplasm." (PMID 39363237, 2024). "In this study, we showed that in a well-studied murine model of human schistosomiasis, Malat1 was dramatically downregulated, differing from other fibrotic disease models." (PMID 39363237, 2024). "To explore the biological effects of Malat1 on schistosomiasis HF, we constructed a Malat1 lentivirus for overexpression and designed the compound of ASO-Malat1 for knockdown in the infected primary HSCs, respectively." (PMID 39363237, 2024). "Thus, we can summarize the mechanism as schistosome infection induces downregulation of Malat1 expression, increasing the miRNA-96 expression by reducing Malat1-mediated endogenous sponging, and elevated miRNA-96 promotes schistosomiasis HF by targeting Smad7." (PMID 39363237, 2024). "Notably, in Malat1-KO mice, knockout of Malat1 aggravates schistosomiasis HF, while restored Malat1 expression in the infected HSCs reduced the expression of profibrogenic genes." (PMID 39363237, 2024). "We next examined the role of Malat1 in the progression of schistosomiasis HF." (PMID 39363237, 2024). "We next examined the role of restored expression of Malat1 in the regulation of schistosomiasis HF." (PMID 39363237, 2024). "Taken together, these data revealed that in the infected mice, knockout of Malat1 gene upregulated miRNA-96 expression, leading to a reduction of Smad7 expression, indicating that the Malat1-mediated suppression of the schistosomiasis HF occurs through the Malat1/miRNA-96/Smad7 axis." (PMID 39363237, 2024). "Therefore, we investigated whether the Malat1-mediated suppression of schistosomiasis HF occurs through the Malat1/miRNA-96/Smad7 axis." (PMID 39363237, 2024). "Therefore, we investigated whether the Malat1-mediated suppression of fibrosis-related genes in the schistosomiasis HF occurs through interaction with miRNAs." (PMID 39363237, 2024). "Furthermore, Malat1 can serve as a biomarker for assessing the response to PZQ treatment, offering potential strategies for intervention of schistosomiasis HF." (PMID 39363237, 2024). "We further demonstrated this in the Malat1-KO infected mice, showing that Malat1 knockout significantly upregulated miRNA-96 expression, leading to reduced Smad7 expression and elevated expression of profibrogenic genes α-SMA, Col1α1 and Col3α1, resulting in a more severe schistosomiasis HF." (PMID 39363237, 2024).
signet ring cell carcinoma (1 paper, 2017). A usually aggressive, poorly differentiated invasive adenocarcinoma characterized by the presence of malignant glandular cells in which the nucleus is pressed to one side by the presence of intracytoplasmic mucus. "Patients with poorly differentiated histology or signet ring cell carcinoma had higher expression of MALAT1 compared to well to moderately differentiated adenocarcinoma (p = 0.030)." (PMID 28077118, 2017).
Sleep apnea (1 paper, 2026). An intermittent cessation of airflow at the mouth and nose during sleep is known as sleep apnea. "This aligns with studies showing fibroblast-enriched lncRNAs (e.g., H19 and MALAT1) regulate fibrosis, but LncRNA-IH is distinct in its hypoxia-dependent induction—linking environmental stress (e.g., sleep apnea-related hypoxia) to fibroblast activation." (PMID 41563538, 2026).
spinal cord ischemia (1 paper, 2019). Reduced blood flow to the spinal cord which is supplied by the anterior spinal artery and the paired posterior spinal arteries. "MALAT1 exhibits a neuroprotective role in spinal cord ischemia–reperfusion injury through miR‐204 regulation." (PMID 31050183, 2019).
Splenomegaly (1 paper, 2021). Abnormal increased size of the spleen. "The presence of constitutional symptoms was significantly associated with higher plasma levels of MALAT1 (p = 0.0302) or GAS5 (p = 0.0306), whereas splenomegaly was correlated to higher LINC01268 (p = 0.0012), MALAT1 (p < 0.0001) or GAS5 levels (p = 0.0006)." (PMID 34638230, 2021).
T cell lymphomas (1 paper, 2017). "In summary, the expression of MALAT1 was increased in T and NK cell lymphoma, and high MALAT1 expression was associated with inferior overall survival, especially for patients with mature T cell lymphoma subtypes." (PMID 28412742, 2017). "During the sequential processes of PRC pathway activation and chromatin remodeling in T cell lymphomas, MALAT1 may directly and specifically bind to PRC pathway proteins, particularly EZH2 and SUZ12, members of the PRC2 family, which may in turn induce H3K27me3." (PMID 28412742, 2017). "Direct binding of MALAT1 to the PRC2 components (EZH2 and SUZ12) was observed in a T cell lymphoma cell line; however, no direct binding of MALAT1 with H3K27me3 and BMI1 (a PRC1 component) was observed." (PMID 28412742, 2017).
tauopathy (1 paper, 2025). Neurodegenerative disorders involving deposition of abnormal tau protein isoforms (tau proteins) in neurons and glial cells in the brain. "The conservation of certain molecular signatures between the THY-Tau22 model and human AD data, particularly genes such as Malat1 and Mbp, suggests common pathogenic mechanisms in tau-mediated neurodegeneration across tauopathies." (PMID 40336141, 2025).
tendinopathy (1 paper, 2022). "However, the mechanisms underlying the role of MALAT1 in tendinopathy are still unclear." (PMID 35635083, 2022). "Consistent with the results of experiments on TDSCs, MALAT1 expression was downregulated in tendinopathy rats." (PMID 35635083, 2022). "Finally, MALAT1 expression was downregulated in tendinopathy rats, and MALAT1 overexpression healed tendon injury in them." (PMID 35635083, 2022). "Our results therefore indicate that targeting the MALAT1/miR-378a-3p/MAPK1 axis may be a promising avenue for the treatment of tendinopathy." (PMID 35635083, 2022). "Therefore, in this study, we aimed to explore the role of MALAT1 in tendinopathy both in vivo and in vitro." (PMID 35635083, 2022).
testicular tumor (1 paper, 2019). "Gonadotropin-releasing hormone treatment may protect against testicular tumor development by downregulating oncogenes, such as MALAT1, mTOR, C-MYC, and EZH2 to enable normal germ cell development." (PMID 31890219, 2019).
thymic carcinoma (1 paper, 2022). Thymic carcinoma (TC) is a type of thymic epithelial neoplasm characterized by a high malignant potential. "Recently, the expression of MALAT1 has been a focus in our studies where the relationship between lncRNA MALAT1 and METTL3, a methyltransferase enzyme that catalyzes the N6-methyladenosine (m6A) modification, were described in the thymic carcinoma cell line, TC1889." (PMID 35529877, 2022).
thyroid nodule (1 paper, 2021). A small circumscribed mass in the THYROID GLAND that can be of neoplastic growth or non-neoplastic abnormality. "Next, analysis of suspicious thyroid nodules versus the contra-lateral tissue revealed that expression of MALAT1, HOTAIR, PVT1, and NEAT1 was significantly higher in malignant lesion than in contra-lateral normal tissue (P < 0.05)." (PMID 33030666, 2021). "The expressions of MALAT1, HOTAIR, PVT1 and the cytological class of a cohort of n = 34 thyroid nodules have been used to fit kernel distributions with Epanechnikov bases functions and positive support to determine the likelihoods p(MALAT1|tum)." (PMID 33030666, 2021). "Hence, each thyroid nodule has been classified as malignant if the probability p(mal.|MALAT1,HOTAIR,PVT1,cyt)." (PMID 33030666, 2021).
tyrosinemia (1 paper, 2026). An autosomal recessive inherited metabolic disorder caused by mutations in the FAH, HPD, and TAT genes. "Correlation analysis revealed a positive association between NEAT1 expression and AST and ALP levels, whereas MALAT1 was inversely correlated with INR in the tyrosinemia group." (PMID 41736130, 2026).
ulcerative colitis (1 paper, 2024). An inflammatory bowel disease involving the mucosal surface of the large intestine and rectum. "Meanwhile, MALAT1 has been linked to the ulcerative colitis clinical subtype of IBD." (PMID 39337694, 2024).
ulcers (1 paper, 2019). "One week later, ulcers were surgically made in the right limb, after which the mice received intradermal transplantation of either mull-MSCs, or as-miR-205-5p-MSCs, or MALAT1-MSCs at the ulcer site." (PMID 31866580, 2019). "VEGF protein was examined in the ulcer tissue 4 weeks after MSC transplantation and shown that more VEGF in MALAT1-MSCs-transplanted tissue, than in as-miR-205-MSCs-transplanted tissue, than in null-transplanted tissue, than STZ without transplantation." (PMID 31866580, 2019).
ventricular septal defect (1 paper, 2024). The presence of a defect (opening) in the septum that separates the two ventricles of the heart. "In the Chinese population, the MALAT1 rs619586 A>G polymorphism is associated with a minimal, non-significant increase in the risk of ASD progression, with a significant association noted in ventricular septal defect progression." (PMID 39172906, 2024).
viral hepatitis (1 paper, 2025). An acute or chronic inflammation of the liver parenchyma caused by viruses.
cancer (1,118 papers, 2009 to 2026). A tumor composed of atypical neoplastic, often pleomorphic cells that invade other tissues. "Specifically, Malat1 expression levels, a long non-coding RNA associated with cancer progression, were elevated with aging, suggesting increased tumorigenic susceptibility in this model." (PMID 40986521, 2025). "MALAT1 (metastasis-associated lung adenocarcinoma transcript 1) is a prominent lncRNA that is known to be associated with many cancer cell lines and tumors." (PMID 39798064, 2025). "One lncRNA that promotes metastasis of various cancer types is metastasis-associated lung adenocarcinoma transcript 1 (MALAT1); therefore, MALAT1 has emerged as a drug target, most notably its 3′ end." (PMID 41226238, 2025). "Malat1 is regulated epigenetically through histone demethylase JMJD2C at H3K9me3 and H3K36me3 locations of the Malat1 promoter, causing its upregulation and subsequent activation of Wnt signaling in cancer metastasis." (PMID 41256287, 2025). "The Metastasis‐Associated Lung Adenocarcinoma Transcript 1 (MALAT1) controls gene expression and alternative splicing functions while its abnormal control has been associated with cancer development in lung cancer and breast cancer and colorectal cancer cases." (PMID 40959208, 2025). "Beyond their roles in transcriptional control, both NEAT1 and MALAT1 have also been implicated in ferroptosis and drug resistance regulation across multiple cancer types." (PMID 41294881, 2025). "Malat1 gene product is a long non-coding RNA that regulates gene expression and is linked to various types of cancer." (PMID 40986521, 2025). "The biological implications of this regulation are particularly relevant in the biology of cancer, as both miR-34a and MALAT1 ncRNAs have been implicated in tumor progression." (PMID 40863726, 2025). "MALAT1, as a highly expressed lncRNA in various tumor tissues, holds the potential to serve as a diagnostic and therapeutic target in cancer." (PMID 40597438, 2025). "MALAT-1, short for Metastasis-associated lung adenocarcinoma transcript 1, is well-known for fueling cancer." (PMID 41029313, 2025). "Another lncRNA investigated, MALAT1, has been found to undergo copy number alterations, translocations, or mutations in various types of cancer." (PMID 40004468, 2025). "Collectively, these findings demonstrate that MALAT1 functions as a key oncogenic lncRNA in HBV-related HCC by orchestrating a broad network of cancer-associated signaling pathways." (PMID 40860202, 2025). "Malat1 gene product is a long non-coding RNA that functions as a gene expression regulator and is linked to various types of cancer." (PMID 40986521, 2025). "Subsequent studies have shown that MALAT1 is implicated in tumor initiation, progression, and resistance to chemotherapy across multiple cancer types." (PMID 40674376, 2025). "SOX2, PIWI proteins, and MALAT1 are molecular regulators implicated in cancer progression, proliferation, and epithelial-mesenchmal transition (EMT)." (PMID 40674376, 2025). "MALAT1 is a widely studied lncRNA reported in various cancers, including its higher levels in HCC, which are associated with the recurrence and poor prognosis post-liver resection." (PMID 40789840, 2025). "MALAT1 also demonstrated consistent diagnostic performance across cancers, with AUCs between 0.82–0.88." (PMID 40674376, 2025). "For instance, lncRNA PCA3 has emerged as a promising biomarker for early prostate cancer detection, and the aberrant expression of lncRNA MALAT1 in cancer cells underlines its potential as a therapeutic target in cancer treatment." (PMID 39827195, 2025). "In contrast, the lncRNA MALAT-1 caused an opposing influence, exacerbating cancer conditions and contributing to poorer outcomes." (PMID 41029313, 2025). "One such exosomal lncRNA, metastasis-associated lung adenocarcinoma transcript 1 (MALAT1), has been identified as being produced by M2 TAMs, where it promotes both glycolysis and cancer progression." (PMID 40781643, 2025).